INS (insulin)
Diseases named in the same sentence as INS in open-access papers (continued):
Sharing a sentence is not in itself a finding about the gene and the disease.
diabetes (continued). "Changed insulin sensitivity is a biological mechanism that may link membrane fluidity to diabetes risk." (PMID 25344391, 2015). "The present study showed that insulin analogues and NPH could be associated with IAbs production in insulin-treated patients with diabetes." (PMID 25961056, 2015). "It should be viewed in the context of the chronic liver disease associated with obesity and diabetes, where intense behavioral treatment, also leading to improved glucose control, reduced insulin levels and improved insulin sensitivity, is expected to stop liver disease progression." (PMID 25045404, 2014). "Several studies showed that insulin affects the liver apolipoprotein production and regulates the enzymatic activity of lipoprotein lipase and cholesterol ester transport protein, which causes dyslipidemia in diabetes mellitus." (PMID 24918095, 2014). "The HOMA parameters findings however indicate that zinc may play a role in progression of diabetes with results showing that serum zinc concentration is associated with insulin sensitivity in the pre-diabetic group." (PMID 24416185, 2014). "Several budding essential mechanisms for diabetes are characterized by elevation of blood glucose levels caused by decreased production of the hormone insulin and/or increased resistance to the action of insulin by certain cells." (PMID 25542373, 2014). "Since insulin avoids the reduction in mitochondrial oxidative phosphorylation and any increase in oxidative stress that protects against Aβ-protein toxicity, we can infer that diabetes is a risk factor for AD development." (PMID 25346723, 2014). "However, the debate about the role of insulin or glucose in the etiology of diabetes-associated dementia is growing strong." (PMID 24764191, 2014). "Initiating basal insulin therapy in patients with poor glycemic control after the use of metformin is supported by the American Diabetes Association and the European Association for the Study of Diabetes." (PMID 24684803, 2014). "In other words, IGT patients with higher FVFs are more resistant to insulin, and may have a higher risk to develop type 2 diabetes mellitus." (PMID 25343445, 2014). "Furthermore, RasGrf1 has also been implicated in insulin secretion induced by the transient diabetes mellitus gene Zac1." (PMID 25421944, 2014). "Previous studies reported that SNPs of RBP4 could increase diabetes susceptibility and decrease insulin secretion and insulin sensitivity." (PMID 24665145, 2014). "Furthermore, streptozotocin-induced diabetes caused dramatic (P < 0.01) reduction in fasting plasma insulin concentration (below lower limit of detection) and concomitantly 4,3-fold (P < 0.01) elevation in fasting plasma glucose concentration in D group." (PMID 24701589, 2014). "In diabetes, deficiency of insulin in conjunction with glucagon- or catecholamine-stimulated lipolysis increases fatty acid delivery to liver which may lead to ketoacidosis, a life-threatening condition." (PMID 25161769, 2014). "Glycemic instability is a serious problem in patients with insulin-deficient diabetes, and it may be due in part to abnormal endogenous glucagon secretion." (PMID 25393115, 2014). "To investigate the relationship between the use of glucose-lowering drug (metformin, TZDs, sulfonylureas, and insulin) and lung cancer risk in patients with diabetes, we conducted a meta-analysis of existing randomised controlled trials (RCTs) and observational studies." (PMID 24924771, 2014). "In addition to these two main (and a few minor) types of diabetes, there is an inherited, monogenic type of diabetes caused by single-gene mutations in the insulin gene." (PMID 25423173, 2014). "In addition, social isolation leads to the insulin-independent diabetes associated with increased expression of hepatic gluconeogenic genes in KKAy mice." (PMID 24804243, 2014).
diabetes (continued). "Because a linked SNP to NDUFC2 altered the susceptibility to glucose-stimulated insulin secretion, a diabetes-related phenotype, we asked whether the NDUFC2 L46V SNP could alter susceptibility to diabetes." (PMID 25245408, 2014). "This study, using two strains of mice fed a HFD, allowed a separation of the role of glucose and insulin in the development of neuropathy and points towards possible parameters that determine the phenotype of the neuropathy associated with diabetes and/or obesity." (PMID 24764191, 2014). "Notably, higher insulin sensitivity estimated with the Matsuda index is associated with a decreased incidence of diabetes in high-risk populations." (PMID 24981579, 2014). "For this reason, and because of its high expression in tissues that play a pivotal role in the pathogenesis of type 2 diabetes like beta-cells, skeletal muscle and liver, the CT-1 gene (CTF1) would be a promising candidate to associate with diabetes, insulin secretion and insulin sensitivity." (PMID 25025664, 2014). "The positive association between duration of diabetes and fear of hypoglycemia could reflect greater insulin use in patients with a longer duration of disease." (PMID 25433668, 2014). "The sites of naturally occurring insulin mutations determine the age of onset and clinical severity of diabetes, which may range from a mild, accidentally diagnosed hyperglycemia to seriously advanced metabolic disorder." (PMID 25423173, 2014). "While these SNPs are predicted to confer risk for diabetes only when maternally inherited, the risk alleles do not correlate with each other and have opposing effects on docking of insulin granules." (PMID 25071830, 2014). "After adjusting for age, gender, BMI, waist circumference, systolic BP, family history of diabetes, smoking, alcohol drinking, education level, and insulin, the RR (95% CI) of diabetes risk in the highest quartile vs. the lowest quartile of the TG/HDL-cholesterol ratio was 2.209 (1.566–3.115)." (PMID 24587359, 2014). "Any imbalance in the level of insulin causes diabetes mellitus." (PMID 26556194, 2014). "Diabetes mellitus is a metabolic disorder characterized by a loss of glucose homeostasis, with disturbances of carbohydrate, fat, and protein metabolism resulting from defects in insulin secretion, insulin action, or both." (PMID 24967338, 2014). "The purpose of the present study was to evaluate whether human insulin use is associated with increased risk of bladder cancer in patients with type 2 diabetes mellitus, by using the National Health Insurance (NHI) databases of Taiwan." (PMID 24466131, 2014). "Although we observed similar strengths in the associations between a majority of phthalate metabolites and markers of diabetes risk, a few exceptions seem to show stronger associations in women (e.g. MiBP/fasting insulin and MBzP/fasting insulin) or in men (e.g., ∑DEHP/FBG and MCPP/HOMA-IR)." (PMID 24499162, 2014). "The mechanism of statins on glycometabolism, decreased insulin sensitivity, and diabetes risk increase is still unknown." (PMID 24995341, 2014). "Calorie and total fat intake restrictions coupled with moderate intensity aerobic exercises significantly improved diabetes risk factors in healthy normoglycemic adults although normoglycemic adults with glucose, insulin, and lipid abnormalities appear to benefit more." (PMID 25960772, 2014). "The dietary composition associated to physical activity could play a significant role in improving insulin sensitivity and reducing risk of diabetes and its complications." (PMID 25551102, 2014). "The insulin-cancer hypothesis postulates that chronic hyperinsulinemia, a typical hallmark of diabetes, is one of the leading factors responsible for the obesity–cancer connection." (PMID 24904527, 2014).
diabetes (continued). "Thus, the ability of our system to measure insulin production and secretion permits mechanistic evaluation and linkage of candidate human diabetes susceptibility genes to roles in insulin expression, post-translational processing, or secretion." (PMID 25101872, 2014). "A subgroup analysis of insulin use and lung cancer risk in patients with diabetes." (PMID 24924771, 2014). "Others associated diabetes with sugar intake and improper insulin productions." (PMID 24919064, 2014). "Several studies have demonstrated an association of this polymorphism with higher insulin sensitivity, a decreased risk of type 2 diabetes mellitus and its nephropathy and retinopathy, and a lower albumin excretion rate in patients with established diabetes." (PMID 24587794, 2014). "Insulin treatment significantly reversed diabetes-induced cerebral superoxide level loss." (PMID 25223305, 2014). "Diabetes mellitus, also referred to as diabetes, is a growing problem in the modern society characterized by impaired carbohydrate, protein and lipid metabolism caused by insulin resistance and an insufficient amount of insulin secreted." (PMID 24633395, 2014). "In conclusion, ERα mRNA expression is induced in islets from young mice by exposure to hyperglycemia and oxidative stress, and mice of both sexes that selectively lack ERα in the islets are susceptible to both oxidative stress in β-cells and insulin-deficient diabetes." (PMID 24498408, 2014). "By contrast, insulin treatment (4 IU/rat/day) for 1 week significantly attenuated diabetes-induced body weight loss (329 ± 14 vs. 292 ± 11 g, P < 0.05), hyperglycemia (153 ± 10 vs. 460 ± 15 mg/dl, P < 0.001), and hypoinsulinemia (2.04 ± 0.55 vs. 0.56 ± 0.07 μg/l, P < 0.05)." (PMID 25223305, 2014). "In spite of the small case number in this study, we found that there is a decline in fasting plasma insulin levels in diabetes subjects carrying K-alleles compared to those with homozygous EE genotype when adjusted for age, sex, and BMI age- and sex-specific percentiles." (PMID 25309595, 2014). "Improved beta-cell function by 1,25(OH)2D produced by pancreatic beta-cells, improved insulin sensitivity by 1,25(OH)2D in skeletal muscle, liver and adipose tissue, and systemic anti-inflammatory effects of 1,25(OH)2D reduce the risk of developing diabetes." (PMID 25197323, 2014). "Our results also confirm the association of inflammatory markers with adiposity and insulin resistance, since BMI, waist circumference, fasting blood glucose and insulin, and systolic and diastolic BP were all significantly associated with inflammatory markers, especially in women with diabetes." (PMID 25258627, 2014). "The existing therapies with exogenous insulin or hypoglycemic agents for type 1 diabetes (T1D) are also unsatisfactory, since they do not offer a cure and are mostly insufficient for preventing the secondary complications associated with diabetes." (PMID 24734255, 2014). "The mechanisms by which TCF7L2 polymorphisms increase diabetes risk and affect the treatment response to insulin secretagogues were thought to be related to impaired incretin-induced insulin secretion, impaired suppression of glucagon or impaired glucagon-like peptide-1 secretion." (PMID 24906949, 2014). "An emerging body of evidence suggests that phthalates may interfere with glucose homeostasis and insulin sensitivity, leading to an increased risk of diabetes." (PMID 24499162, 2014). "Insulin secretion with high output may be associated with age-related decline in insulin secretion, resulting in a more rapid development of diabetes." (PMID 24971303, 2014). "Therefore, in the present study, we evaluated the effect of insulin treatment on islet transplantation involving a suboptimal amount of islets in Akita mice, which is a diabetes model mouse with an Insulin 2 gene missense mutation." (PMID 24743240, 2014).
diabetes (continued). "Supporting the complexity and the importance of insulin production and secretion, genome-wide association studies have shown that most of the multiple susceptibility genes that facilitate diabetes development are involved in controlling beta-cell mass and function." (PMID 25628604, 2014). "Furthermore, muscle-specific deletion of GLUT4 causes glucose intolerance and diabetes in mice with reduced insulin-stimulated glucose uptake." (PMID 24849570, 2014). "In this study, we tested the hypothesis that chronic exposure to excess long-acting insulin (glargine) can cause typical type 2 diabetes mellitus (T2DM) in normal mice fed on a chow diet." (PMID 24741073, 2014). "Diabetes risk factors are modifiable with healthy behavior change but, sadly, rates of uncontrolled disease are high, both, from lack on adherence to initial oral drug treatment and in the long-term use of insulin." (PMID 24966036, 2014). "Surgically removing visceral fat (VF) depots have led to an improvement in glucose tolerance and insulin sensitivity in laboratory animals, supporting the idea that VF represents ‘bad’ fat and is associated with several disease conditions including diabetes." (PMID 24690289, 2014). "Impairment in beta-cell exocytosis is associated with reduced insulin secretion and diabetes." (PMID 25105407, 2014). "Pre-diabetes and insulin resistance are associated with a chronic but subclinical inflammatory process that impairs insulin action in most tissues and could also hamper pancreatic beta-cell function." (PMID 25393696, 2014). "Secretion of insulin by pancreatic β cells in response to glucose is central for glucose homeostasis, and dysregulation of this process is a hallmark of the early stages of diabetes." (PMID 25144761, 2014). "Diabetes mellitus (DM) is a chronic endocrine disease characterized by disorders in the metabolism of carbohydrates, lipids and proteins due to a deficiency in the insulin production by pancreatic beta cells and/or to an increase in the insulin resistance in peripheral tissues." (PMID 25469699, 2014). "Insulin resistance, a state in which a given concentration of insulin is associated with a subnormal glucose response, and diabetes are both associated with an increased risk of cardiovascular disease and are often accompanied by a constellation of other cardiovascular risk factors." (PMID 25260374, 2014). "Insulin therapy and oral antidiabetic agents/drugs used in the treatment of diabetes mellitus have not sufficiently proven to control hyperlipidemia, which is commonly associated with the diabetes mellitus." (PMID 25525518, 2014). "Increased resistin levels in periodontitis may thus be considered to pose a risk for diabetes by decreasing the insulin sensitivity." (PMID 24692844, 2014). "Immediate insulin therapy prevented the ultrastuctural changes associated with diabetes." (PMID 25145789, 2014). "Bariatric surgery promotes and sustains weight loss, improves pancreatic β-cell function, enhances insulin sensitivity, reduces adiposity, ameliorates diabetes mellitus and other metabolic parameters, as well as improves cardiovascular risk factors and reduces mortality rate." (PMID 24608927, 2014). "Thus, adiponectin reduces the risk of diabetes by regulating insulin signal transduction and insulin resistance." (PMID 24860814, 2014). "Further, insulin sensitivity is improved, and the treatment of endothelial dysfunction may also reduce complications associated with both diabetes and other metabolic disease." (PMID 24772374, 2013). "Untreated depression is associated with worsened diabetes complications such as retinopathy, nephropathy, neuropathy, sexual dysfunction and coronary heart disease, poorer glycemic control, and higher insulin level." (PMID 24199205, 2013). "Previously, diabetes was believed to be caused only by the deficiency of insulin." (PMID 24324517, 2013).
diabetes (continued). "Experimental animal models of diabetes have shown that PG synthesis is active in the presence of insulin deficiency and that plasma and urine lipid oxidation are markedly decreased following insulin analog plus metformin treatment." (PMID 24195588, 2013). "Diabetes mellitus (DM) includes a group of diseases that are characterized mainly by high levels of serum glucose (hyperglycemia) and a deficiency in or resistance to the action of the hormone insulin." (PMID 23984417, 2013). "The insulin gene (INS) is the second well established susceptible locus in Diabetes mellitus." (PMID 24039701, 2013). "Second, compared with humans, normal carnivores appear to have mild glucose intolerance and reduced insulin sensitivity, which offers opportunity to study the metabolic pathways that underlie glucose intolerance and insulin resistance, two hallmarks of diabetes pathology in humans." (PMID 24348462, 2013). "We suggest that the overall control of hyperglycemia in diabetics following the TA1m gene therapy combined with a sensible dietary practice would be superior to the current commonly used insulin injections, and would minimize long-term diabetes-associated systemic damages." (PMID 23826312, 2013). "As a result, although diabetes in these patients was caused by insulin resistance and failure of insulin production as a direct result of hyperinsulinaemia, treatment with exogenous insulin causes necessarily hyperinsulinaemia." (PMID 23983688, 2013). "Insulin adjustment markedly decreased the size of the obesity-diabetes association." (PMID 23806173, 2013). "Altered insulin system is associated with major pathological conditions like diabetes and cancer." (PMID 24051403, 2013). "Impaired glucose tolerance was related to decreased insulin secretory response after glucose load, and decrease in the fasting plasma insulin concentration and loss of insulin secretory response after glucose load were observed after the onset of diabetes." (PMID 23691526, 2013). "This may also suggest the potential mechanism(s) by which alterations in these genes affect diabetes risk (e.g. insulin secretion versus insulin sensitivity)." (PMID 23442068, 2013). "The Cardiovascular Risk Evaluation in people with type 2 Diabetes on Insulin Therapy (CREDIT) study is an international, multicenter, observational study designed to assess metabolic parameters and cardiovascular risk of patients with type 2 diabetes mellitus (T2DM) on insulin therapy." (PMID 24011395, 2013). "Long duration of diabetes may affect the severity of diabetes that is associated with weight loss (low BMI) and history of insulin therapy." (PMID 24033926, 2013). "Changes in the islets of Langerhans by a possible action of the antiretroviral therapy may increase insulin secretion and glucose uptake by cells of the body as an energy source, increasing the concentration of glucose in the blood and thus causing diabetes." (PMID 23856035, 2013). "Diabetes is a metabolic affection characterized by a chronic hyperglycemia resulting from the deficiency of insulin secretion, abnormalities in the action of the insulin or the association of both." (PMID 24244637, 2013). "To test the hypothesis that TLR4 activity is involved in the pathogenesis of insulin-deficient diabetes, we established a NOD mouse line that selectively lacks the expression of TLR4." (PMID 24086519, 2013). "Furthermore, wholegrain foods improve indices of diabetes risk, including glycemic control, fasting plasma insulin and glucose, and insulin sensitivity and also aid in the management of those individuals with or at high risk of developing T2D." (PMID 23679924, 2013). "Due to destruction of β-cells, the decrease in body weight and increase in food and water intake were commonly observed in diabetes and this may be due to metabolic changes caused by lack or deficiency of insulin." (PMID 24416041, 2013).